PLEKHA3 (pleckstrin homology domain containing A3)
Description:
Plays a role in regulation of vesicular cargo transport from the trans-Golgi network (TGN) to the plasma membrane. Regulates Golgi phosphatidylinositol 4-phosphate (PtdIns(4)P) levels and activates the PtdIns(4)P phosphatase activity of SACM1L when it binds PtdIns(4)P in 'trans' configuration. Binds preferentially to PtdIns(4)P. Negatively regulates APOB secretion from hepatocytes.
Synonyms: FAPP1
Tractability: Antibody: UniProt places it where antibodies can reach, with high confidence. PROTAC: ubiquitination databases record sites on it.
Gene: Protein-coding gene on chromosome 2 (178,480,457 to 178,516,463, forward strand). Ensembl gene ENSG00000116095.
Subcellular location: Golgi apparatus, trans-Golgi network membrane
Subcellular location (Human Protein Atlas): Golgi apparatus
Pathways (Reactome):
Metabolism: Synthesis of PIPs at the plasma membrane
Gene Ontology:
Molecular function: identical protein binding; molecular carrier activity; phosphatidylinositol-4-phosphate binding; protein binding
Biological process: endosome organization; phosphatidylinositol biosynthetic process; receptor recycling; retrograde transport, endosome to Golgi
Cellular component: Golgi apparatus; early endosome; Golgi membrane; recycling endosome; trans-Golgi network; cytosol
Genetic constraint (gnomAD): Loss-of-function variants: 14 observed, 31.51 expected, observed/expected ratio (o/e) 0.44, 90% interval 0.29 to 0.69. The upper end of that interval is the gene's LOEUF score, 0.69, which puts it in group 2 of 6, group 1 being the genes least tolerant of losing a copy. Missense variants: 238 observed, 327.79 expected, observed/expected ratio (o/e) 0.73, 90% interval 0.65 to 0.81. Synonymous variants: 94 observed, 113.29 expected, observed/expected ratio (o/e) 0.83, 90% interval 0.7 to 0.99.
Homologues: Orthologues: chimpanzee PLEKHA3 (100% identical), macaque PLEKHA3 (99% identical), dog PLEKHA3 (97% identical), guinea pig PLEKHA3 (94% identical), mouse Plekha3 (91% identical), rabbit PLEKHA3 (90% identical), rat Plekha3 (88% identical), pig PLEKHA3 (85% identical), tropical clawed frog plekha3 (77% identical), zebrafish plekha3 (68% identical), Caenorhabditis elegans F49D11.10 (21% identical), Caenorhabditis elegans Y82E9BR.14 (6% identical), and 2 more. Paralogues in human: PLEKHA8 (51% identical), CERT1 (25% identical), GLTPD2 (7% identical), CPTP (6% identical), GLTP (5% identical).
Diseases named in the same sentence as PLEKHA3 in open-access papers:
PLEKHA3 is named in the same sentence as 2 diseases in open-access papers, as found by Europe PMC text mining. Sharing a sentence is not in itself a finding about the gene and the disease. The quoted sentences say what the papers report.
dilated cardiomyopathy (1 paper, 2025). Cardiomyopathy which is characterized by dilation and contractile dysfunction of the left and right ventricles. "It is worth noting that FKBP7, PRKRA, and third gene (PLEKHA3, significant with LVM, LVEDV, and LVESV), all lie within a region of chromosome 2 that also includes the gene TTN, which is well established heritable cause of dilated cardiomyopathy, a leading cause of heart failure." (PMID 39670392, 2025).
PLEKHA3 also shares sentences with these, for which no sentence is quoted: infection (2 papers).